OR4K2 (olfactory receptor family 4 subfamily K member 2)
Description:
Odorant receptor.
Synonyms: OR14-15
Tractability: Antibody: UniProt places it where antibodies can reach, with medium confidence; UniProt predicts a signal peptide or a membrane-spanning region; its Gene Ontology location is reachable by antibodies, with medium confidence.
Gene: Protein-coding gene on chromosome 14 (19,875,142 to 19,883,932, forward strand). Ensembl gene ENSG00000165762.
Subcellular location: Cell membrane
Pathways (Reactome):
Sensory Perception: Expression and translocation of olfactory receptors
Gene Ontology:
Molecular function: olfactory receptor activity; G protein-coupled receptor activity
Biological process: detection of chemical stimulus involved in sensory perception of smell; G protein-coupled receptor signaling pathway
Cellular component: plasma membrane; membrane
Genetic constraint (gnomAD): Loss-of-function variants: 9 observed, 12.67 expected, observed/expected ratio (o/e) 0.71, 90% interval 0.43 to 1.24. The synonymous counts are far from expectation, so gnomAD's model fits this gene poorly and the ratio says little. Missense variants: 535 observed, 383.01 expected, observed/expected ratio (o/e) 1.4, 90% interval 1.3 to 1.5. Synonymous variants: 175 observed, 132.92 expected, observed/expected ratio (o/e) 1.32, 90% interval 1.16 to 1.49.
Homologues: Orthologues: chimpanzee OR4K2 (99% identical), macaque OR4K2 (97% identical), dog OR4K2 (88% identical), rabbit OR4K2 (87% identical), pig OR4K2 (85% identical), rat Or4k2 (83% identical), mouse Or4k2 (83% identical), guinea pig OR4K2 (52% identical). Paralogues in human: OR4K14 (61% identical), OR4K15 (61% identical), OR4K1 (58% identical), OR4K17 (57% identical), OR4K13 (56% identical), OR4K5 (55% identical), OR4F4 (54% identical), OR4F5 (54% identical), OR4L1 (54% identical), OR4F17 (54% identical), OR4F6 (52% identical), OR4F15 (52% identical), and 116 more.
Diseases named in the same sentence as OR4K2 in open-access papers:
OR4K2 is named in the same sentence as 3 diseases in open-access papers, as found by Europe PMC text mining. Sharing a sentence is not in itself a finding about the gene and the disease.
OR4K2 shares sentences with these, for which no sentence is quoted: bipolar disorder (1 paper); neurodegenerative disease (1); Parkinson disease (1).